CDKN1A (cyclin dependent kinase inhibitor 1A)
Diseases named in the same sentence as CDKN1A in open-access papers (continued):
Sharing a sentence is not in itself a finding about the gene and the disease.
lupus (2 papers, 2012 to 2015). "We then confirmed that these genes, such as IL32, CD226, CDKN1A, and PTPRN2 were similarly hypomethylated in lupus patients of African-American compared to European-American descent." (PMID 26609326, 2015).
mantle cell lymphoma (2 papers, 2022). Mantle cell lymphoma is a rare form of malignant non-Hodgkin lymphoma affecting B lymphocytes in the lymph nodes in a region called the ``mantle zone''. "Subsequent study has been demonstrated that ARV-771 can also suppress proliferation of mantle cell lymphoma cells via increasing the levels of tumor suppressors, including CDKN1A/p21, HEXIM1, and NOXA." (PMID 35600879, 2022).
mastitis (2 papers, 2025 to 2026). Inflammation of breast tissue during lactation or postpartum due to an obstructed duct or infection. "Comparing genes that express at a different level and the protein network, we identified three key genes (CDKN1A, FKBP5 and SLC7A5) and pathways that mastitis includes both in clinical and subclinical form." (PMID 42127079, 2026).
medullary thyroid carcinoma (2 papers, 2019 to 2020). "In this largest SNP risk association study for medullary thyroid carcinoma (MTC), a significant protective risk association of CDKN1A Ser31Arg SNP with MTC was shown for the first time." (PMID 31408923, 2019).
metastatic melanoma (2 papers, 2021 to 2023). A melanoma that has spread from its primary site to another anatomic site. "At the same time, when comparing the transcriptomes of primary and metastatic melanoma, CDKN1A was also down-regulated in metastatic melanoma which has higher malignancies." (PMID 38070141, 2023). "EZH2 is another factor expressed in metastatic melanoma; its depletion has been shown to restore P21/CDKN1A expression and arrest cell proliferation." (PMID 34198989, 2021). "Among them, CDKN1A, CDKN2A, CXCR4 and RAD51 were significantly down-regulated in metastatic melanoma when compared with the primary type." (PMID 38070141, 2023).
multiple endocrine neoplasia (2 papers, 2023 to 2025). Multiple endocrine neoplasia (MEN) is a group of rare inherited cancer syndromes characterized by the development of two or more endocrine gland tumors, sometimes with tumor development in other tissues or organs. "These abnormalities are often linked to syndromes such as Multiple Endocrine Neoplasia (MEN-1, MEN-2A, MEN-4) or mutations in genes such as CASR, CDKN1A, CDKN1B, CDKN2C, and RET." (PMID 41597072, 2025).
muscle atrophy (2 papers, 2021 to 2022). The loss of muscle tissue due to inactivity or disease. "The increase of CDKN1A expression level can also be found in the muscle atrophy model induced by starvation.Similarly, the expression of CDKN1A increased in the model of muscle atrophy induced by hindlimb suspension, but decreased after reloading." (PMID 35847900, 2022).
ovarian tumor (2 papers, 2013 to 2015). "Overexpression of the p21-encoding CDKN1A is correlated with a low malignant potential of an ovarian tumor." (PMID 25875127, 2015). "Two other candidates that have not previously been tested as RGs in ovarian tumour tissue, ABL1 and CDKN1A, were selected from the commercial gene array." (PMID 24001041, 2013).
pilocytic astrocytoma (2 papers, 2019 to 2024). Pilocytic astrocytoma is a rare subtype of low-grade glioma of the central nervous system characterized by a well circumscribed, often cystic, brain tumor with a discrete mural nodule and long, hair-like projections that extend from the neoplastic astrocytes.
psoriasis (2 papers, 2017 to 2021). An autoimmune condition characterized by red, well-delineated plaques with silvery scales that are usually on the extensor surfaces and scalp. "Cytosine-guanine hypomethylation in p15/CDKN2B and p21/CDKN1A genes involved in cell cycling has been observed in mononuclear cells isolated from bone marrow of patients with psoriasis." (PMID 29232931, 2017). "To further validate findings from our transcriptional analysis, we performed immunohistochemical analysis focusing on selected apoptotic and cell cycle regulatory proteins (FOSL1, GDF15, JUNB and CDKN1A) in lesional psoriasis skin (control) and 24 h after 311 nm or 290 nm irradiation." (PMID 33812333, 2021).
skin papilloma (2 papers, 2014). A benign papillary neoplastic growth on the skin composed of epithelial cells and a fibrous stalk. "In skin papillomas, deletion of HUWE1 stabilizes MIZ1 and enhances repression ofCdkn2b (p15INK4b) and Cdkn1a (p21CIP1) by the MYC/MIZ1 complex,correlating with enhanced tumorigenesis." (PMID 25253726, 2014).
soft tissue sarcoma (2 papers, 2008 to 2018). A malignant neoplasm arising from muscle tissue, adipose tissue, blood vessels, fibrous tissue, or other supportive tissues excluding the bones. "CDKN1A can act as apositive regulator of senescence-like terminal proliferation arrest, but its function seems neither sufficient nor absolutely required for a treatment response to doxorubicin in tumor cells, especially soft tissue sarcoma." (PMID 18959781, 2008).
staphylococcus aureus infection (2 papers, 2024 to 2025). An infectious process in which the bacteria Staphylococcus aureus is present. "On the other hands, the pathway of Staphylococcus Aureus infection highly enriched in CD82 and MIOX, the pathway of proteasome highly enriched in CDKN1A and MYCN." (PMID 39966875, 2025).
steatosis (2 papers, 2023 to 2024). Increased lipid within the cytoplasm of cells. "Compared with the control group, Nqo1, Atf3, and Cdkn1a were up-regulated in MCD diet-fed mice, and gradually increased with the aggravation of steatosis and inflammation." (PMID 37305039, 2023).
suppressor tumors (2 papers, 2021).
thyroid tumor (2 papers, 2019 to 2020). A benign or malignant neoplasm affecting the thyroid gland.
urothelial carcinoma (2 papers, 2022 to 2024). A malignant neoplasm derived from the transitional epithelium of the urinary tract (urinary bladder, ureter, urethra, or renal pelvis). "Combined FIGHT-201 (n = 149) and FIGHT-207 (n = 13) data for patients with urothelial carcinoma identified TSC1, which was reported in earlier analysis and CDKN1A, which was now found to be correlated nominally significantly with objective response." (PMID 38710951, 2024).
acne (1 paper, 2023). An inflammatory process of the sebaceous glands which is characterized by comedones, nodules, papules and/or pustules on the skin.
acromegaly (1 paper, 2020). Acromegaly is an acquired disorder related to excessive production of growth hormone (GH) and characterized by progressive somatic disfigurement (mainly involving the face and extremities) and systemic manifestations. "Sixteen patients with acromegaly and PHP underwent rigorous genetic testing with DNA sequence analysis performed for genes including: MEN1, CDC73, CDKN1A, CDKN1B, CDKN2B, CDKN2C, and AIP, as well as MLPA to search for deletions or duplications in MEN1, CDC73, CDKN1B, and AIP genes." (PMID 32311048, 2020).
adult T cell leukemia (1 paper, 2019). "In addition, ANRIL, frequently overexpressed and tumorigenic in a panel of cancers, forms a ternary complex with EZH2 and P65, and epigenetically marks and represses P21/CDKN1A transcription in adult T cell leukemia." (PMID 31752930, 2019).
AIDS (1 paper, 2019). A syndrome resulting from the acquired deficiency of cellular immunity caused by the human immunodeficiency virus (HIV). "We propose that the coordinated upregulation of CDKN1A, IER3, GADD45B and TNF as well as the positive regulation of calcium-dependent signaling could be involved in the mechanisms leading to the slower progression to AIDS and HIV control concomitantly observed in EC-LTNPs." (PMID 31582776, 2019).
angina (1 paper, 2025). "The CpG site cg11407210 in the LTA gene was associated with increased risk of MI, CHD, and angina, while cg14437551 in the CDKN1A gene was linked to increased risk of MI, CHD, and angina." (PMID 41420191, 2025).
angiosarcoma (1 paper, 2013). A malignant tumor arising from the endothelial cells of the blood vessels. "We validated this data via Western and immunofluorescence analysis of Cdkn1a and Cdkn1b (p21 and p27, respectively) in SVR angiosarcoma lines treated for 24 hours with sham or 100 μM propranolol, revealing significant upregulation of both proteins following propranolol treatment." (PMID 23555867, 2013).
atrophic gastritis (1 paper, 2025). "We also identified several upregulated genes involved in the cell cycle G1/S phase transition in mucous neck cells, including SMARCC2, BCL7C, and CDKN1A, indicating that mucous neck cells acquired an aberrant cell proliferation phenotype in the atrophic gastritis stage." (PMID 39905493, 2025).
autosomal dominant polycystic kidney disease (1 paper, 2020). Autosomal dominant form of polycystic kidney disease. "In contrast, in autosomal dominant polycystic kidney disease (ADPKD), where CDKN1A levels are typically low, there is some evidence suggesting that roscovitine-mediated restoration of senescence, as measured by increased SA-β Gal and CDKN1A expression, is beneficial and halts cystic progression." (PMID 32369550, 2020).
beta thalassemia (1 paper, 2024). Beta-thalassemia (BT) is characterized by deficiency (Beta+) or absence (Beta0) of synthesis of the beta globin chains of hemoglobin (Hb). "Elevated levels of Cdkn1a mediate erythroblast apoptosis in beta-thalassemia but do not improve erythropoiesis." (PMID 39231178, 2024).
bronchopulmonary dysplasia (1 paper, 2020). Bronchopulmonary dysplasia is a chronic respiratory disease that results from complications related to lung injury during the treatment of infant acute respiratory distress syndrome in low-birth-weight premature infants or from abnormal lung development in older infants. "CDKN1A expression is upregulated in long-term oxidative stress-induced experimental bronchopulmonary dysplasia and in a hyperoxia-induced lung injury rat model." (PMID 32457348, 2020).
carcinoids (1 paper, 2015). "ASCL1 (p = 0.0016), BCL2 (p < 0.0001), CASP8 (p = 0.0030), CCNE1 (p = 0.0135), CDK1 (p = 0.0146), CDK2 (p = 0.0114), CDKN1A (p = 0.0107) and CDKN2A (p = 0.0002) showed lower expression in carcinoids compared to carcinomas." (PMID 26008974, 2015).
cataract (1 paper, 2024). Partial or complete opacity of the crystalline lens of one or both eyes that decreases visual acuity and eventually results in blindness. "Based on this, it was speculated that PDGFRB and CDKN1A were promoting genes, and PTEN, CANX, COL4A2, EIF2S1, and NPM1 were suppressing genes in cataract pathogenesis." (PMID 38662949, 2024).
chondrosarcoma (1 paper, 2018). A malignant cartilaginous matrix-producing mesenchymal neoplasm arising from the bone and soft tissue. "Similarly, Fgf signaling induces Cdkn1a-mediated cell cycle arrest in chondrocytes and further, ectopic Fgf20 induces growth arrest of rat chondrosarcoma cells in vitro." (PMID 30063206, 2018).
chronic cervicitis (1 paper, 2024). Chronic inflammation of the cervix. "We used a set of patient-derived precancerous (n = 32) and noncancerous (chronic cervicitis; n = 10) tissue samples to investigate the gene expression of several OIS (LMNB1, CDKN2A, CDKN2B, and CDKN1A), and SASP (IL1A, CCL2, TGFB1, CXCL8, and MMP9) biomarkers using qRT-PCR." (PMID 39727946, 2024).
clear-cell renal cell carcinoma (1 paper, 2014). "This may act to counter the proliferative effects of MYC, cyclin D1 and MDM2; however, and concerningly, CDKN1A is also overexpressed in clear-cell renal cell carcinoma relative to normal kidney." (PMID 24827579, 2014).
colorectal adenocarcinoma (1 paper, 2019). The most common type of colorectal carcinoma. "However, that was not the case for CDKN1A, as depletion of the Inr sequence (+7 to +16 bp from the TSS) did not affect MYC repression of CDKN1A promoter in colorectal adenocarcinoma cells." (PMID 30909496, 2019).
congenital heart disease (1 paper, 2022). A heart disease that is present at birth. "In summary, we found a relationship between CDKN1A and inflammation after CPB for congenital heart disease by WGCNA, experiments and various bioinformatics methods." (PMID 36090322, 2022).
cutaneous melanoma (1 paper, 2022). A primary melanoma arising from atypical melanocytes in the skin. "Lastly, we treated three cutaneous melanoma cell lines with Nutlin-3 for 24 h and investigated the mRNA expression of RFX7, RFX5, PNRC1, PDCD4 and CDKN1A as positive control." (PMID 36139642, 2022). "In the cutaneous melanoma cell lines, MEL 04.01 and MEL 06.24, Nutlin-3 treatment increased significantly CDKN1A, CYFIP2 and PTCHD4 expression, whereas PIK3IP1 and MXD4 levels do not or hardly change." (PMID 36139642, 2022).
cyst (1 paper, 2022). A sac-like closed membranous structure that may be empty or contain fluid or amorphous material. "While CDKN1B and CDKN1C expression was higher in normal subtypes, senescence-related CDK inhibitors CDKN1A and CDKN2A were more abundant in PKD-CDC subtypes, suggesting that cyst-lining cells may be prone to cellular senescence due to cellular stress." (PMID 36310237, 2022).
DiGeorge syndrome (1 paper, 2023). "CDKN1A is a reported target gene in a mouse TBX1 deletion model of the DiGeorge syndrome, highlighting CDKN1A as a general target of TBX1." (PMID 38203204, 2023).
embryonal carcinoma (1 paper, 2020). A non-seminomatous malignant germ cell tumor characterized by the presence of large germ cells with abundant cytoplasm resembling epithelial cells, geographic necrosis, high mitotic activity, and pseudoglandular and pseudopapillary structures formation. "Previously, induction of CDKN1A expression is also demonstrated in F9 murine embryonal carcinoma cells and HEK293 human embryonic kidney cells upon transient HNF4α transfection." (PMID 31695151, 2020).
endothelial dysfunction (1 paper, 2021). In vascular diseases, endothelial dysfunction is a systemic pathological state of the endothelium (the inner lining of blood vessels) and can be broadly defined as an imbalance between vasodilating and vasoconstricting substances produced by (or acting on) the endothelium. "Indeed, the pro-angiogenic microRNA-93 promoted angiogenesis on a mouse model of hind limb ischemia through inhibition of Cyclin-dependent kinase inhibitor 1A, which has been linked with endothelial dysfunction and is implicated in the development of PAD." (PMID 34513927, 2021).
ependymoma (1 paper, 2009). A WHO grade II, slow growing tumor of children and young adults, usually located intraventricularly. "It was observed that in ependymomas, 66.67% did not express the CDKN1A protein, whereas the others did so." (PMID 20169278, 2009).
familial isolated hyperparathyroidism (1 paper, 2023). A rare, autosomal dominant hereditary syndrome characterized by hypercalcemia, abnormally high levels of parathyroid hormone, and isolated hyperfunctioning parathyroid tumors. "Non-syndromic hereditary hyperparathyroidism, called familial isolated hyperparathyroidism (FIHP), can be caused by the incomplete manifestation of mutations of syndrome-related genes such as MEN-1, CDC73, GCM2, CDKN1A, CDKN1B, or CDKN2C." (PMID 36900197, 2023).
gastric ulcer (1 paper, 2018). An ulcerated lesion in the mucosal surface of the stomach.
gastritis (1 paper, 2018). Inflammation of the stomach. "Luteolin from Aurantii Fructus and quercetin from licorice can interact with the same target CDKN1A, which has effects on treatment of gastritis." (PMID 29861771, 2018).
glaucoma (1 paper, 2023). Increased pressure in the eyeball due to obstruction of the outflow of aqueous humor. "Our data also revealed an obvious dysregulation of MYC and CDKN1A expression in the conjunctiva of glaucoma patients with hyperfibrosis." (PMID 37569323, 2023).
growth disorders (1 paper, 2021). "Interestingly, multiple sox family members (sox5, sox6, sox8, and sox18) were significantly dysregulated in shox-deficient pectoral fins together with other genes (nppa, nppc, cdkn1a, cdkn1ca, cyp26b1, and cy26c1), highlighting an important role for these genes in shox-related growth disorders." (PMID 34122528, 2021).
Hepatic steatosis (1 paper, 2015). Steatosis is a term used to denote lipid accumulation within hepatocytes. "In contrast, one cancer-inhibiting gene p21/WAF1 (Cdkn1a) was up-regulated in SO-HFD but it is also considered to be an epiobesogene and is linked to hepatic steatosis and liver dysfunction in offspring born to mothers fed a high fat diet." (PMID 26200659, 2015).
Hyperoxaluria (1 paper, 2025). Increased excretion of oxalates in the urine. "Mechanistically, CDKN1A plays a crucial role in in ferroptosis regulation, such as attenuating ferroptosis induced by hyperoxaluria in renal tubular epithelial cells." (PMID 41188368, 2025).
hypothyroidism (1 paper, 2024). Abnormally low levels of thyroid hormone. "The relative expression of three cell cycle promoters (CDK1, CDK2, and CDK4), and one cell cycle inhibitor (CDKN1A) was compared in each tissue to determine the effect of hypothyroidism on the developing fetus." (PMID 38902754, 2024). "This apparent cell cycle suppression without a corresponding increase in CDKN1A is consistent with prior findings regarding PRRSV-induced fetal hypothyroidism, which suggests that PRRSV may indirectly supress muscle cell proliferation in utero by first reducing circulating thyroid hormone levels." (PMID 38902754, 2024).
ICF syndrome (1 paper, 2017).
intestinal cancer (1 paper, 2010). "We used the computational method to elucidate the connections between a well-known driver gene of intestinal cancer, Apc (adenomatous polyposis coli), to another gene also involved in cancer, Cdkn1a (previously known as p21)." (PMID 20824133, 2010).
iron deficiency (1 paper, 2025). "Genes identified by RNA-seq as induced during iron deficiency also displayed an enrichment of the activating histone marks, H3K4me3 and H3K27ac at transcription start sites (TSSs) in the low iron condition (e.g. Cdkn1a) when analysed by ChIPmentation." (PMID 40541943, 2025).
laryngeal carcinoma (1 paper, 2024). Carcinoma that arises from the laryngeal epithelium. "According to Chernock RD, patients with CDKN1A (P21) positive laryngeal cancer have a better prognosis." (PMID 38032489, 2024).